ODCP (ornithine decarboxylase pseudogene)
Synonyms: formerly ODC2
Gene: Processed pseudogene on chromosome 7 (129,028,889 to 129,030,527, forward strand). Ensembl gene ENSG00000244556.
Diseases named in the same sentence as ODCP in open-access papers:
ODCP is named in the same sentence as 3 diseases in open-access papers, as found by Europe PMC text mining. Sharing a sentence is not in itself a finding about the gene and the disease.
ODCP shares sentences with these, for which no sentence is quoted: infection (2 papers); cancer (1); virus infection (1).